CD4 (CD4 molecule)
Diseases named in the same sentence as CD4 in open-access papers (continued):
Sharing a sentence is not in itself a finding about the gene and the disease.
lymphedema (continued). "Reductions in both CD3 and CD4 T cell infiltration were observed in the VLNT group in comparison to the lymphedema group (CD3: 12.00 ± 5.94 vs 24.13 ± 4.2911 cells/HPF; CD4: 30.33 ± 13.33 vs 52.33 ± 28.44 cells/HPF, p < 0.0001)." (PMID 36176614, 2022). "For example, in a mouse model of lymphedema, the tissue demonstrated increased CD4+ T cell numbers and T-helper 2 (Th2) differentiation." (PMID 35743063, 2022). "Recent advances reveal that the activation and accumulation of CD4+ T cells are key in the development of lymphedema." (PMID 35886961, 2022). "Although CD4+ cell recruitment regulates fibrosis formation in lymphedema the function of macrophages is less clear in lipedema." (PMID 36605202, 2022). "Using flow cytometry, we found that TGF‐β1 neutralisation decreases the percentage of leukocytes, CD4+ cells, Th1 cells, Th2 cells and neutrophils in the skin, suggesting that this treatment has broad anti‐inflammatory effects in lymphedema." (PMID 35652284, 2022). "Immune cell recruitment (macrophages, fibroblasts, CD4+ T cells, and Th2 cells) has also been shown to facilitate adipose deposition and fibrosis in lymphedema." (PMID 35743063, 2022). "AT from lymphedema contained more CD45Ro expressing cells and activated CD4+ lymphocytes (CD4/CD25 +) including their subtypes (TH1, TH2, TREG, TH17)." (PMID 33854130, 2021). "Previous studies have identified CD4+ T helper cells as key drivers of lymphedema progression, including their roles in increasing tissue fibrosis and reducing lymphatic function." (PMID 33923272, 2021). "Our data suggests that CD4+ T cells increase as a percentage of T cells within the dLNs during lymphedema progression." (PMID 33923272, 2021). "Once in the skin, CD4+ T cells promote changes such as impaired lymphangiogenesis, fibrosis, and increased inducible nitric oxide synthase (iNOS) expression leading to lymphedema." (PMID 32268536, 2020). "Interactions between CD4+ T-cells and macrophages have been implicated in numerous studies in adversely driving lymphedema pathogenesis, and depletion of CD4+ cells ameliorates lymphedema in most mouse models." (PMID 31320677, 2019). "Histological and flow cytometry analysis of tissue biopsies from patients with lymphedema as well as mouse models of lymphedema demonstrate that the predominant inflammatory cell infiltrate is comprised of CD4+ cells." (PMID 30936872, 2019). "In fact, the severity of lymphedema correlates significantly with the degree of CD4+ cell inflammatory response." (PMID 30936872, 2019). "Such immune cell populations can be important for development of lymphedema, for example a CD4+ cell inflammatory response and T-helper 2 (Th2) cell differentiation can contribute to key pathological changes including fibrosis and lymphatic dysfunction." (PMID 30761143, 2019). "Ultimately, the elucidation of the mechanisms by which CD4+ T cells promote lymphedema is important because it allows for the identification of potential therapeutic targets." (PMID 29773802, 2018). "Collectively, our results suggest that lymphatic injury results in tissue changes that drive CD4+ T cell activation and differentiation in skin-draining lymph nodes and that this immunologic response has a key role in lymphedema pathogenesis." (PMID 29773802, 2018). "Further evaluation is required to further clarify the interplay between Th1 and Th2 cells, in addition to the roles of other, rarer, CD4+ effector cells, but such results corroborate the potential benefit of targeting Th2 cells in lymphedema." (PMID 29773802, 2018). "A previous study showed the importance of CD4+ T cells and their cytokines in the pathology of lymphedema." (PMID 30111321, 2018). "Taken together, these findings confirm that the migration of CD4+ T cells from lymph nodes to skin is critical to lymphedema." (PMID 29773802, 2018).
lymphedema (continued). "Here the authors show how these cells contribute to lymphedema and identify that the sphingosine-1-phosphate receptor modulator FTY720 can prevent lymphedema in a mouse tail injury model by blocking the release of CD4+ T cells from the lymph nodes to the skin." (PMID 29773802, 2018). "Our group has previously shown that CD4+ T cell numbers are increased in human lymphedema biopsy samples and, more importantly, that the number of tissue-infiltrating CD4+ T cells has a linear positive correlation with disease severity." (PMID 29773802, 2018). "Here we show that CD4+ T cells are necessary for lymphedema pathogenesis by utilizing adoptive transfer techniques in CD4 knockout mice that have undergone tail skin and lymphatic excision or popliteal lymph node dissection." (PMID 29773802, 2018). "Although it is clear that CD4+ T cells are important in lymphedema pathophysiology, few studies have defined the mechanisms regulating T cell activation, differentiation, and homing to lymphedematous tissues." (PMID 29773802, 2018). "Patients with late-stage lymphedema had significantly more infiltrating T cells in general, specifically more CD4+ cells, than those with early-stage disease." (PMID 28186091, 2017). "More recently, we have shown that CD4+ cells play a crucial role in the regulation of fibrosis in both clinical and animal models of lymphedema." (PMID 28186091, 2017). "Taken together, the collective findings of these studies from three separate laboratories suggest that lymphedema results in increased tissue infiltration of CD4+ cells in lymphedematous tissues of mice and humans." (PMID 28106728, 2017). "Studies of the CD4+ cells in lymphedema have shown that T regulatory cells (Tregs) comprise a notable proportion of the inflammatory infiltrate in both mouse models of lymphedema and human biopsy samples." (PMID 28106728, 2017). "The CD4+ cell response in lymphedema, similar to other fibroproliferative disorders, is characterized by a mixed Th1/Th2 cell population." (PMID 28186091, 2017). "Our lab has shown the importance of CD4+ cells and their cytokines in the pathology of lymphedema, as well as the development of fibrosis observed with lymphatic injury." (PMID 28186091, 2017). "Nine patients (24%) developed concomitant facial lymphoedema, and these patients had a significantly lower CD4+ T-cell count (28 cells/mm3) compared to the rest of the group (130 cells/mm3) (P = 0.01)." (PMID 23008762, 2012). "In order to determine how CD4+ cell inflammation contributes to pathology of lymphedema, we analyzed tissue fibrosis and regulators of extracellular matrix deposition." (PMID 23185491, 2012). "Lymphedema and lymphatic stasis result in CD4+ cell inflammation and infiltration of mature T-helper cells." (PMID 23185491, 2012). "However, to understand the dynamics of CD4+ cell infiltration, it is necessary to analyze immune responses in the early stages of lymphedema development." (PMID 39941140, 2025). "CD4+ T cells isolated from lymphedema liposuction fluid stimulated ex vivo with a peptide pool from human insulin also demonstrated increased frequencies of antigen-activated T cells (CD4+CD45RO+CD154+) compared with autologous T cells from blood in a patient with normal BMI (*p<0.05)." (PMID 40821816, 2025). "Our results showed that dLNs transplantation induced CD4+ T cells infiltration, suggesting dLNs may draw CD4+ T cells from affected limbs to dLNs, thus preventing lymphedema progression." (PMID 41244341, 2025). "Furthermore, as Tregs are known to increase during the development of lymphedema, we examined the infiltration of CD4+Foxp3+ Tregs into lymphedema tissues at each time point." (PMID 39941140, 2025). "Studies in mouse models demonstrate that depletion of CD4+ T cells prevents lymphedema development." (PMID 40821816, 2025). "CD4+ T cell infiltration is considered essential for the progression of lymphedema." (PMID 39941140, 2025).
lymphedema (continued). "LNs have been proven to play a vital role in CD4+ T cells migration in lymphedema." (PMID 41244341, 2025). "In some cases, insulin-activated T cells may contribute to early disease, since previous studies have identified CD4+ T cells in general as important mediators of lymphedema." (PMID 40821816, 2025). "Besides the innate immune system, the CD4+ lymphoid cell population presents another promising target in lymphedema, with an extensive number of pre-clinical and clinical studies focusing on the CD4+ cell dynamics." (PMID 39737964, 2024). "In a mouse tail surgery and popliteal lymph node dissection (PLND) model, more than 70% of the inflammatory response was composed of CD4+ T cells, and when CD4+ T cells were depleted, the onset of lymphedema could be prevented." (PMID 39045461, 2024). "In fact, an increasing number of publications elaborating on the role of the CD4+ cells in lymphedema suggest that immunomodulation may critically influence the onset and development of the condition." (PMID 39737964, 2024). "Additionally, PD-1, Lag-3, and PD-1+Tim-3+ expression on CD4+ T cells showed a significant upregulation in patients with lymphedema compared to HCs." (PMID 37250774, 2023). "IL-17A production in CD4+, CD4+PD-1+, and CD4+PD-1- cells was downregulated in post-LVA compared to that in lymphedema (2.7 [1.8–3.3] vs. 1.6 [0.9–2.3], p = 0.01; 5.5 [3.6–6.3] vs. 4.0 [2.7–4.5], p = 0.04; and 1.3 [0.8–2.5] vs. 0.8 [0.4–1.6], p = 0.01, respectively)." (PMID 37250774, 2023). "In addition, in animals with lymphedema and S. epidermidis infection, we observed less activated CD4+ MHC class II+ T helper lymphocytes." (PMID 38137455, 2023). "In contrast, IFN-γ expression in CD4+PD-1- cells was similar between lymphedema and post-LVA." (PMID 37250774, 2023). "Furthermore, inflammatory cytokine production from CD4+ T cells indicated that LVA can ameliorate chronic inflammation in lymphedema." (PMID 37250774, 2023). "PD-1, Tim-3, and PD-1+Tim-3+ expression on CD4+ T cells showed significant downregulation in post-LVA compared to lymphedema; 30.7 (19.8–39.1)% vs. 27.1 (17.6–35.4)%, p = 0.03; 1.4 (0.9–3.0)% vs. 1.0 (0.7–1.4)%, p < 0.01; and 0.7 (0.4–1.1)% vs. 0.3 (0.2–0.6)%, p < 0.01, respectively." (PMID 37250774, 2023). "Importantly, our model does re-create the increased CD4+ T cell infiltration observed in the tail lymphedema model." (PMID 38131378, 2023). "An increased infiltration of CD4+ cells was observed only in secondary lymphedema when compared to both the control and lipedema tissues, (C = 18.63 ± 3.405 cells/field, L = 21.48 ± 9.087 cells/field, LE = 34.86 ± 14.40 cells/field, H = 28.35 ± 11.05 cells/field)." (PMID 37108757, 2023). "In addition to CD4+ T cell infiltration, increase in regulatory T cells (Tregs), phenotypically characterized as FOXP3-expressing CD4+ T cells, was observed in lymphedema." (PMID 36386144, 2022). "Human tissue samples from limbs with lymphedema confirm elevated CD4+ T cell quantities that correlate with lymphedema stage, and thus, restoring normal T cell function may improve lymphedema." (PMID 35743063, 2022). "This hypothesis is supported by studies using the mouse tail lymphedema models, in which CD4 knockout mice were less likely to develop lymphedema and the depletion of regulatory T cells (Tregs) exacerbated lymphedema." (PMID 35886961, 2022). "The lymphedematous tissue displayed various known hallmarks of lymphedema compared to the healthy controls, such as increased epidermis thickness, collagen deposition in the periadipocyte space and the distinct infiltration of CD4+ cells." (PMID 36421681, 2022). "Therefore, the activation of CD4+ T cells through antigen presentation by DCs is the key process in the development and exacerbation of lymphedema." (PMID 35886961, 2022).
lymphedema (continued). "In fact, a previous study has suggested that CD4+ T cells migrate from dLNs to sites of injury during lymphedema development, although the mechanisms facilitating this migration remain unclear." (PMID 33923272, 2021). "Indeed, recent work from our own laboratory indicates CD4+ T cell activation is necessary and sufficient for the development of lymphedema." (PMID 32268536, 2020). "Studies by the group of B. J. Mehrara and M. Detmar showed in clinical and experimental lymphedema that the majority of the cells that accumulate chronically in lymphedematous tissues are CD4+ T cells and that they contribute to the pathological changes including fibrosis." (PMID 32256375, 2020). "In subcutaneous tissue of the mouse tail, CD4+ cell infiltration was significantly increased in obese mice at baseline and the presence of lymphedema in obese mice greatly increased both CD45+ and CD4+ cell infiltration as well as subcutaneous adipose deposition." (PMID 32477160, 2020). "CD4-deficient mice were protected from developing lymphedema following tail lymphatic ablation; similar findings were noted when CD4+ T cells were depleted using neutralizing antibodies in wild-type (WT) mice." (PMID 32268536, 2020). "While global deletion of CD4+ cells restricted lymphedema development in the mouse tail lymphedema model used in this study, targeted depletion of Tregs led to exacerbated edema associated with increased infiltration of immune cells and a mixed Th1/Th2 cytokine profile." (PMID 30761143, 2019). "Lymphedematous skin from clinical biopsy specimens and mouse models of lymphedema are infiltrated with large numbers of CD4+ cells that co-express interferon gamma (IFN-γ; putative Th1 cells) and CD4+ cells that co-express interleukin 4 (IL4) or IL13 (putative Th2 cells)." (PMID 30936872, 2019). "It is now clear that CD4+ T cells play a major role in the development of secondary lymphedema, at least in animal models, although the effect of these cells on lymphangiogenesis in lymphedema differed in different mouse models and therefore requires further clarification." (PMID 30761143, 2019). "Importantly, DC activation or migration was identical in wild-type and CD4KO mice suggesting that DC activation precedes chronic CD4+ cell inflammatory reactions in lymphedema." (PMID 30936872, 2019). "CD4+ T cells are known to have a central function in lymphedema." (PMID 29773802, 2018). "Given our findings of the spatiotemporal patterns of CD4+ T cells in lymphedema, we hypothesized that inhibition of the release of CD4+ T cells from lymph nodes would prevent lymphedema." (PMID 29773802, 2018). "We next aimed to elucidate the mechanisms by which CD4+ T cells promote lymphedema." (PMID 29773802, 2018). "Consistent with the spatiotemporal patterns of CD4+ T cells, we also show that blocking release of T cells from lymph nodes using a sphingosine-1-phosphate receptor modulator is effective at preventing lymphedema in a mouse tail model of lymphatic injury." (PMID 29773802, 2018). "CD4+ T cells are critical for the development of lymphedema." (PMID 29773802, 2018). "KS-IRIS was defined as ≥2 of the following: abrupt increase in number of KS lesions, appearance or exacerbation of lung-opacities or lymphedema, concomitantly with an increase in CD4+ cell-count ≥50 cells/mm3 and a decrease of >1 log in viral-load once started cART." (PMID 28558783, 2017). "In addition, we have shown that CD4+ cells play an important role in the regulation of lymphangiogenesis in lymphedema and inflammatory lymphangiogenesis." (PMID 23185491, 2012). "Loss of CD4+ but not CD8+ or CD25+ cell inflammation markedly decreases the pathological changes associated with lymphedema." (PMID 23185491, 2012). "Since CD4 depletion after lymphatic injury resulted in decreased lymphedema, we hypothesized that CD4 cells may be responsible for regulating inflammatory changes in tissues exposed to lymphatic fluid stasis." (PMID 23185491, 2012).
lymphedema (continued). "To elucidate the role of CD4+ T cell subsets in the development of lymphatic pathology, we examined specific sets of cytokines in individuals with filarial lymphedema in response to parasite antigen (BmA) and compared them with responses from asymptomatic infected individuals." (PMID 19381284, 2009). "Similarly, we observed higher frequencies of antigen-activated CD4+ T cell populations in lymphedema liposuction fluid (CD4+CD45RO) than in autologous blood on flow cytometry, supporting a local T cell response to antigens in lymphedema that is absent systemically." (PMID 40821816, 2025). "A study showed that upon lymphatic injury, CD4+T cells get activated into a mixed Th1 and Th2 phenotype by dendritic cells in the regional lymph nodes and then migrate to the injury site to initiate lymphedema pharmacological inhibition of T cell release from the lymph nodes." (PMID 37974224, 2023). "Upregulated exhaustion markers on CD4+ T cell populations in lymphedema might reflect not only chronic consumption of effector CD4+ T cells but also the counterbalancing enhancement of suppressed function to inhibit the progress of tissue inflammation and fibrosis." (PMID 37250774, 2023). "In the future, the treatment of lymphedema should focus on lymphatic regeneration and on improving the microenvironment of the edematous region, such as the suppression of fibrosis and infiltration of inflammatory cells, and the regulation of CD4+ T cell balance." (PMID 35886961, 2022). "Furthermore, the interaction of CD4+ T cells and macrophages has been shown to play a role in driving proliferation of lymphatic endothelial cells and aberrant lymphangiogenesis, which contribute to interstitial fluid accumulation in lymphedema." (PMID 30761143, 2019). "Thus, strategies targeting generalized CD4+ inflammatory responses or inhibition of Th2 differentiation may hold clinical promise for treating lymphedema." (PMID 28186091, 2017). "Considering that CD4+ T cells, and their cytokines, play a critical role in lymphedema pathology, the purpose of this study was to evaluate the efficacy of the immunosuppressive drug, tacrolimus, applied topically for the prevention and treatment of lymphedema." (PMID 28186091, 2017). "Therefore, since the increase in Il1rl1 indicates the induced infiltration of ST2+ cells, IL-33 may be involved in the infiltration of other ST2+ cells besides IL-13-expressing ILC2, leading to CD4+ T cell and Treg cell infiltration during lymphedema development." (PMID 39941140, 2025). "Studies have shown that skin CD4+ T cells infiltration is increased in CRL patients and is the main driver of lymphedema progression." (PMID 41244341, 2025). "The number of CD4 cells that expressed Th2 cytokine IL4 and IL5 was increased in patients with lymphedema." (PMID 37886950, 2023). "In comparison to that in HCs, the IFN-γ production in CD4+, CD4+PD-1+, CD8+, and CD8+PD-1- T cells was significantly upregulated in patients with lymphedema." (PMID 37250774, 2023). "In the present study, the expression of PD-1, Tim-3, and PD-1+Tim-3+ on CD4+ and CD8+ T cells in lymphedema was significantly downregulated in post-LVA, which still showed upregulated expression, compared with that in HCs." (PMID 37250774, 2023). "Although the activated complement and CD4+ T cells mainly accumulated around lymphatic vessels, the TUNEL+ cells were detected throughout the lymphedema tissue." (PMID 37940849, 2023). "To understand the correlation between cytokine production by T cells and lymphedema, we compared the expression of IFN-γ, IL-4, and IL-17A on CD4+ and CD8+ T cells in lymphedema, post-LVA, and HCs." (PMID 37250774, 2023). "IFN-γ levels in CD4+PD-1+ T cells and IL-17A levels in CD4+ T cells were downregulated in post-LVA compared with lymphedema." (PMID 37250774, 2023).